SIDT1 (SID1 transmembrane family member 1)
Description:
In vitro binds long double-stranded RNA (dsRNA) (500 and 700 base pairs), but not dsRNA shorter than 300 bp. Not involved in RNA autophagy, a process in which RNA is directly imported into lysosomes in an ATP-dependent manner, and degraded.
Synonyms: FLJ20174; SID-1; SID1
Tractability: Small molecule: a structure with a bound ligand is known. Antibody: UniProt predicts a signal peptide or a membrane-spanning region; its Gene Ontology location is reachable by antibodies, with medium confidence. PROTAC: its protein half-life has been measured.
Gene: Protein-coding gene on chromosome 3 (113,532,400 to 113,629,714, forward strand). Ensembl gene ENSG00000072858.
Subcellular location: Membrane
Gene Ontology:
Molecular function: cholesterol binding; double-stranded RNA binding; RNA transmembrane transporter activity
Biological process: RNA transport
Cellular component: lysosome; plasma membrane; membrane
Genetic constraint (gnomAD): Loss-of-function variants: 63 observed, 63.86 expected, observed/expected ratio (o/e) 0.99, 90% interval 0.8 to 1.22. The upper end of that interval is the gene's LOEUF score, 1.22, which puts it in group 5 of 6, group 1 being the genes least tolerant of losing a copy. Missense variants: 854 observed, 820.55 expected, observed/expected ratio (o/e) 1.04, 90% interval 0.98 to 1.1. Synonymous variants: 331 observed, 316.9 expected, observed/expected ratio (o/e) 1.04, 90% interval 0.95 to 1.14.
Homologues: Orthologues: chimpanzee SIDT1 (99% identical), macaque SIDT1 (98% identical), rabbit SIDT1 (93% identical), pig SIDT1 (92% identical), mouse Sidt1 (92% identical), dog SIDT1 (92% identical), rat Sidt1 (86% identical), tropical clawed frog sidt1 (67% identical), guinea pig SIDT1 (51% identical), Caenorhabditis elegans chup-1 (31% identical). Paralogues in human: SIDT2 (58% identical).
Diseases named in the same sentence as SIDT1 in open-access papers:
SIDT1 is named in the same sentence as 17 diseases in open-access papers, as found by Europe PMC text mining. Sharing a sentence is not in itself a finding about the gene and the disease. The quoted sentences say what the papers report.
liver fibrosis (3 papers, 2021 to 2023). "Furthermore, the authors showed that dietary absorption of miRNAs (plant-derived miR-2911) prevented the liver fibrosis that occurred in SIDT1-deficient mice." (PMID 37627960, 2023). "Notably, dietary miRNAs absorbed via SIDT1 can exert biological functions in the host, and oral administration of plant-derived miR2911 retards liver fibrosis, which is abolished by SIDT1 deficiency." (PMID 32801357, 2021). "Furthermore, oral administration of plant-derived miR2911 retards liver fibrosis, and this protective effect was abolished in SIDT1-deficient mice." (PMID 32801357, 2021). "Dietary miR2911 absorbed via SIDT1 are secreted and inhibited CCl4-induced liver fibrosis in Sidt1+/+ mice, but failed in Sidt1−/− mice, suggesting that miR2911 absorbed via SIDT1 secreted and played biological roles in vivo." (PMID 34187513, 2021). "In the IV injection groups, elevated miR2911 levels, suppressed expression of TGF-β1, decreased hepatic hydroxyproline levels and alleviated liver fibrosis were all observed in the livers of both Sidt1+/+ and Sidt1−/− mice." (PMID 32801357, 2021). "A recent study has proved that miR2911 absorbed via SIDT1 transporter suppressed the expression of TGF-β1, resulting in alleviation of CCl4-induced liver fibrosis." (PMID 34187513, 2021). "In contrast, oral administration of miR2911 failed to alleviate liver fibrosis in Sidt1−/− mice." (PMID 32801357, 2021).
breast carcinoma (2 papers, 2014 to 2022). "Our data show that the expression of POLR3G in breast cancer samples was negatively correlated with that of eight out of ten genes (GATA3; XBP1; AGR2; SIDT1; AR; SPDEF; FOXA1; MLPH) in a list of signature genes most differentially expressed in luminal A compared to basal-like tumors." (PMID 36497214, 2022).
breast tumors (1 paper, 2022). "The top eight genes that negatively correlated to POLR3G expression (MLPH, FOXA1, SPDEF, AR, SIDT1, AGRP2, XBP1, GATA3) are typically overexpressed in ER+ breast tumors as compared to ER- breast tumors." (PMID 36497214, 2022).
colon cancer (1 paper, 2025). "Honeysuckle-derived miR2911 exhibits anti-tumor effects in colon cancer by targeting TGF-β1 mRNA in tumor-bearing wild type Sidt1+/+ and nude type Sidt1-/- mouse models." (PMID 40362513, 2025).
colorectal adenocarcinoma (1 paper, 2021). The most common type of colorectal carcinoma. "ELISA was performed to determine the expression level of TGF-β1 of mouse colorectal adenocarcinoma CT26 cells when treated with miR2911 and tumor tissue in Sidt1+/+ and Sidt1−/− mice." (PMID 34187513, 2021).
Hyperglycemia (1 paper, 2022). An increased concentration of glucose in the blood. "The SIDT1 gene is associated with insulin secretion, and its expression was decreased in individuals with hyperglycemia." (PMID 36046788, 2022).
insomnia (1 paper, 2020). A sleep disorder characterized by difficulty in falling asleep and/or remaining asleep. "Two examples of this include FLOT2 (p = 3.97 × 10−05 with intelligence), which encodes the neuronal signaling factor flotillin-2, and SIDT1 (p = 1.34 × 10−05 with insomnia), which is a dsRNA transporter." (PMID 32413284, 2020).
non–small cell lung cancers (1 paper, 2024). A group of at least three distinct histological types of lung cancer, including non-small cell squamous cell carcinoma, adenocarcinoma, and large cell carcinoma. "SIDT1 plays a key role in breast, pancreatic, and non–small cell lung cancer." (PMID 38237680, 2024). "Previous studies on mammalian SIDT1 and SIDT2 have implicated them in various biological processes such as glucose and lipid metabolism, immune response, and tumorigenesis, including breast, lung, gastrointestinal, pancreatic and non–small cell lung cancers, but the specific mechanisms are unknown." (PMID 38237680, 2024).
oligodendroglioma (1 paper, 2012). A well-differentiated (WHO grade II), diffusely infiltrating neuroglial tumor, typically located in the cerebral hemispheres. "Three additional gene transcripts, CAP2, RELN and SIDT1, showed >20-fold increase in the level of latent splicing in Grade III oligodendroglioma compared to normal cells." (PMID 23002147, 2012).
infection (8 papers, 2008 to 2023). The state of being infected such as from the introduction of a foreign agent such as serum, vaccine, antigenic substance or organism. "After 1–3 days of infection, the medium was cleared of cells and large debris by centrifugation and filtration and assessed for the presence of soluble SidT1 ECD." (PMID 22509261, 2012). "The post-infection medium contained a soluble protein that could be purified by Ni-affinity chromatography and, judging from SDS PAGE, was the approximate molecular weight of the SidT1 ECD." (PMID 22509261, 2012). "Anti-His6 Western blots also revealed the presence of a soluble protein with the approximate size of the SidT1 ECD in the medium 24–48 hours post infection, and tandem liquid chromatography mass spectrometry (MS) identified the isolated protein as SidT1 (data not shown)." (PMID 22509261, 2012).
tumor (3 papers, 2011 to 2025). "To examine the effect of SIDT1 on miR2911, we adopted a CT26 tumor model in Sidt1+/+ and Sidt1−/− mice." (PMID 34187513, 2021). "In the gavage groups, dramatically increased miR2911 levels were detected in the blood and tumor of Sidt1+/+ mice, and consequently, the expression of TGF-β1 was significantly suppressed." (PMID 34187513, 2021).
SIDT1 also shares sentences with these, for which no sentence is quoted: cancer (1 paper); neurodegenerative disease (1); pancreatic ductal adenocarcinoma (1); septicemia (1); synucleinopathies (1); viral infection (1).